HGF (hepatocyte growth factor)
Diseases named in the same sentence as HGF in open-access papers (continued):
Sharing a sentence is not in itself a finding about the gene and the disease.
lung carcinoma (continued). "For example, it has been demonstrated that lung cancer cells with amplified MET become dependent on HGF under pharmacological MET inhibition." (PMID 27121052, 2016). "In a recent study, PHA665752 has similarly been shown to block HGF induced effects on lung cancer cells." (PMID 26310485, 2015). "In the present study, we have described for the first time that a traditional Chinese medicine formula, YangZheng XiaoJi has a profound direct effect on HGF induced aggressiveness of human lung cancer cells, both in vitro and in vivo." (PMID 26310485, 2015). "demonstrate that the E3 ligase HUWE1 degrades the RAC activator TIAM1 following HGF stimulation, promoting cell junction disassembly, motility, and invasion in epithelial cells including lung cancer cells." (PMID 25543140, 2015). "In the present study, we investigated the effect of a traditional Chinese medicine reported in cancer therapies, namely YangZheng XiaoJi (YZXJ) on lung cancer and on HGF mediated migration and invasion of lung cancer cells." (PMID 26310485, 2015). "YangZheng XiaoJi also exhibited an effect on HGF- and HGF/EGF-induced cellular migration on lung cancer cells and impacted on the phosphorylation of the HGF receptor, cMET." (PMID 26310485, 2015). "Several compounds against MET/HGF are in clinical trial and have been shown to be active against lung cancer." (PMID 25884481, 2015). "They found that miR-34 was able to overcome HGF-induced gefitinib resistance in HCC827 and PC-9 cells by modulating c-Met and downstream pathway molecules, suggesting a new strategy for reversing HGF-induced resistance to gefitinib in lung cancers." (PMID 28536397, 2015). "YZXJ has a significant role in reducing the migration, invasion and in vivo tumour growth of lung cancer and acts to inhibit the migratory and invasive effects induced by HGF and indeed by HGF/EGF." (PMID 26310485, 2015). "HGF is one of the most powerful motogens (motility stimulating cytokines) which, together with the HGF receptor, cMET, are aberrantly expressed in lung cancer." (PMID 26310485, 2015). "In the present study, we sought to investigate the effects of YangZheng XiaoJi on the migration, invasion and cell adhesion of lung cancer cells, in particular in the context of stimulation by HGF." (PMID 26310485, 2015). "Most importantly, we provided strong evidence showing that the tumorigenic and scattering effect of HGF/SF on the A549 lung carcinoma cells can be attenuated by H19 knockdown." (PMID 25884481, 2015). "Both lung cancer cells increased their migration in response to HGF and responded to YZXJ by reducing their speed of migration." (PMID 26310485, 2015). "MET is a receptor for hepatocyte growth factor and a tyrosine kinase (receptor-type tyrosine kinase), and supports the initial steps of invasion and metastasis of most human cancers, including lung cancer." (PMID 26325180, 2015). "EGFR signaling has been shown to enhance HGF-induced c-MET phosphorylation levels in lung cancer cell lines." (PMID 26260789, 2015). "Blocking HGF/cMET pathways by way of small kinase inhibitors, neutralising antibodies and antagonist have been shown to be viable new treatments for lung cancer." (PMID 26310485, 2015). "The current study has shown that the Chinese medicine, YangZheng XiaoJi, has a strong inhibitory effect on HGF induced cellular migration of the lung cancer cells tested." (PMID 26310485, 2015). "In lung cancer, HGF has also been shown to interfere with EGF tyrosine kinase activation, which in turn results in induced resistance to EGFR inhibitor therapies." (PMID 26310485, 2015). "Circulating HGF (cHGF) was found to be a regular feature for patients with lung cancer and has been suggested to be a useful biomarker in choosing a HGF/cMET based targeted therapy." (PMID 26310485, 2015). "HGF, and indeed its receptor cMET, are a pair of proteins that have been found to be frequently over-expressed in clinical lung cancers." (PMID 26310485, 2015).
lung carcinoma (continued). "HGF and IL-6 have been shown to cooperatively enhance lung cancer cell invasion by upregulation of their corresponding cell surface receptors." (PMID 26268945, 2015). "The targeted therapy to HGF/c-Met signal pathway is a new highlight in the treatments of lung cancer.In this review, we will discuss the dysregulation of HGF/c-Met signal pathway in lung cancer and the new progress for the targeted drugs to this pathway." (PMID 25130970, 2014). "Our current study is preclinical, and we demonstrated that mTOR inhibitors showed considerable efficacy in lung cancer cells with HGF-mediated resistance to EGFR-TKI resistance both in vitro and in vivo." (PMID 23690929, 2013). "Another study noted that the overexpression of CHIP inhibited the lung cancer cell growth and invasion mediated by Met (the receptor for hepatocyte growth factor)." (PMID 23426273, 2013). "We, thus, need to demonstrate the precise mechanisms by which bufalin overcame HGF-triggered resistance to apoptosis in EGFR-mutant lung cancer." (PMID 23533466, 2013). "This indicates that HGF is an ideal target for overcoming EGFR-TKI resistance in EGFR mutant lung cancer patients." (PMID 23690929, 2013). "In the present study, we demonstrated that mTOR inhibitors suppressed the growth of EGFR mutant lung cancer cells, even in the presence of HGF, in vitro and in vivo." (PMID 23690929, 2013). "We previously reported that HGF induces EGFR-TKI-resistance in EGFR mutant lung cancer cells by restoring MET/PI3K/AKT pathway signaling." (PMID 23690929, 2013). "We previously reported that this pathway is also crucial for acquiring HGF-triggered resistance to EGFR-TKIs in EGFR mutant lung cancer cells." (PMID 23690929, 2013). "Many studies recently reported that HGF induced resistance to reversible EGFT-TKIs in EGFR mutant lung cancer cells by activating Met and the downstream phosphoinositide 3-kinase (PI3K)/Akt pathway." (PMID 23533466, 2013). "Vanillin also inhibits cell migration of human lung cancer cells induced by hepatocyte growth factor (HGF)." (PMID 23971004, 2013). "Lung cancer cell lines made resistant to EGFR-TKIs by the gatekeeper EGFR-T790M mutation, Met amplification, and HGF overexpression and mice with tumors induced by these cells were treated with crizotinib and a new generation EGFR-TKI." (PMID 24386407, 2013). "Recent studies showed that HGF is involved in the carcinogenesis, invasion/motility, EMT, angiogenesis, and metastasis in lung cancer, and it is therefore associated with poor prognosis of patients." (PMID 23690929, 2013). "Actually, MET tyrosine phosphorylation occurs in A549 lung carcinoma cells within 10 min after HGF addition, while NK4 inhibits the HGF-mediated MET activation." (PMID 23296269, 2013). "Our results also suggest that mTOR inhibitors have advantage of several mechanisms to suppress the growth of EGFR-TKI resistance triggered by HGF in EGFR mutant lung cancer cells." (PMID 23690929, 2013). "It is interesting that claudin-7 expressing human lung cancer cells have been shown to have a reduced response to HGF, are less motile, and form fewer foot processes than untreated cells." (PMID 22559840, 2012). "Two HGF antibodies that target the aberrant action of HGF are currently being tested in lung cancer patients." (PMID 22363766, 2012). "LMH 87 inhibited HGF/SF-induced migration of SK-OV-3 ovarian carcinoma cells, the proliferation of A549 lung cancer cells and the growth of human U87MG glioma cells in a mouse xenograft model." (PMID 22511956, 2012). "The c-MET ligand HGF can also be overexpressed by tumor cells with moderate expression observed in 45% of lung cancer tumors." (PMID 22363766, 2012). "We have also previously demonstrated a reinforcing loop of c-Met-EGFR cross-activation initiated by HGF in lung cancer, that occurs via COX-2 activation and involves direct phosphorylation of c-Met by EGFR ligands." (PMID 21390244, 2010).
lung carcinoma (continued). "Therefore, targeting the HGF/MET axis in EGFR TKI-resistant lung cancer has emerged as a promising strategy to overcome EGFR TKI resistance." (PMID 38338342, 2024). "The HGF/c-MET axis is associated with Wnt/β-catenin signaling, with studies indicating that Wnt/β-catenin signals Snail1 and Zeb1 regulate bone metastasis in lung cancer." (PMID 39201787, 2024). "HGF itself is also highly expressed in EGFR TKI-resistant lung cancer." (PMID 38338342, 2024). "The interaction between lung cancer cells and cancer-associated fibroblasts (CAFs) occurs via the HGF/c-Met signaling pathway, whereby lung cancer cells stimulate CAFs to release HGF, leading to the activation of c-MET and subsequent promotion of lung cancer cell proliferation and survival." (PMID 39201787, 2024). "Metformin, one of the most useful blood glucose-lowering drugs, improved survival in EGFR lung cancer and could be used to overcome HGF resistance to Alectinib." (PMID 37444532, 2023). "Recent research found that an anti-HGF monoclonal antibody can inhibit HGF-induced angiogenesis and tumor growth in preclinical models of lung cancer, providing a potential therapeutic strategy for lung cancer patients." (PMID 37760616, 2023). "This study reveals miR-144-3p/HGF axis may be involved in the suppression of lung cancer cellular proliferation and development, and miR-144-3p may function as a potential therapeutic target in lung cancer treatment in the future." (PMID 35568918, 2022). "In our research, HGF acts more as a protective factor to inhibit the progression of lung cancer." (PMID 35664309, 2022). "MiR-144-3p can function as a potential inhibitor to suppress lung cancer development by binding to HGF, and miR-144 could serve as an effective biomarker in lung cancer diagnosis." (PMID 35568918, 2022). "Moreover, after detection of HGF expression in various lung cancer cell lines, it was shown that mRNA levels of HGF were higher in six lung cancer cell lines compared to normal lung cells." (PMID 35568918, 2022). "In agreement with this, our results indicated that HGF exhibited high expression in lung cancer tissues and cell lines, suggesting HGF could be a regulator contributing to lung cancer development." (PMID 35568918, 2022). "Epithelial-to-mesenchymal transition (EMT) appears to be crucial process in lung cancer cell invasion and metastasis, and Hepatocyte growth factor (HGF) is reported to make contribution to EMT in cancer development, which includes liver cancer, colorectal carcinoma, and prostate cancer." (PMID 35568918, 2022). "More importantly, miR-144-3p/HGF signaling pathway could be an important regulator in EMT in lung cancer cell metastasis." (PMID 35568918, 2022). "Since patients who developed EGFR mutant lung adenocarcinomas with acquired resistance to EGFR inhibitor drugs (gefitinib or erlotinib) exhibit increased copy numbers of MET, c-Met-HGF inhibitors are used for lung cancer treatment alone or in combination with other drugs." (PMID 35986321, 2022). "For example, in EGFR-mutant lung cancer, HGF may be involved in endogenous and acquired resistance to acid kinase inhibitors." (PMID 34745947, 2021). "CAF-derived HGF inhibits paclitaxel-induced apoptosis of lung cancer cells by upregulating the PI3K/Akt pathway and glucose-regulated protein 78 (GRP78), a protective chaperone protein that supports cell survival and is associated with the development of chemoresistance." (PMID 33673405, 2021). "Besides, miR-1-3p sensitizes HGF-induced gefitinib-resistant human lung cancer cells through suppression of c-Met signaling and EMT." (PMID 33514309, 2021). "Additionally, lung cancer cells can secrete a variety of cytokines to promote the continuous secretion of HGF by peripheral fibroblasts, thus forming a positive feedback loop, leading to the infinite growth of cancer cells." (PMID 34122599, 2021).
lung carcinoma (continued). "Similarly, overexpression of HGF and/or its receptor c-Met have been reported in lung cancer cell lines and patients." (PMID 34299042, 2021). "Exploring further mechanisms by which curcumin may inhibit HGF signalling in lung cancer should contribute to the mechanistic scrutiny applied when considering the utility of curcumin in therapeutic prevention regimens." (PMID 31963196, 2020). "In addition, miR-206 has been shown to sensitize HGF-induced gefitinib-resistant human lung cancer cells through inhibition of c-Met signaling and the EMT." (PMID 32219093, 2020). "Finally, serum levels of HGF have been associated with resistance to EGFR inhibitors in KRAS wild-type metastatic colorectal cancer and lung cancer." (PMID 32545260, 2020). "There is increasing emphasis on the importance of the c-Met/HGF pathway in lung cancer progression and promotion of resistance resulting from Met amplification, exon 14 mutation, or activation due to HGF expression, with small molecule Met inhibitors and anti-HGF antibodies now in clinical trials." (PMID 31963196, 2020). "The HGF/c-Met axis also contributes to drug resistance in lung cancer." (PMID 32083078, 2020). "Because autocrine HGF-MET signaling has been previously shown to play a critical role in lung cancer progression and co-overexpression of HGF with MET is not uncommon, it is attractive to propose targeting HGF-MET also as a potential strategy to curb resistance to EGFR-TKIs." (PMID 31815659, 2019). "Another experiment showed that stromal fibroblast could induce resistance to epidermal growth factor receptor (EGFR) tyrosine kinase inhibitors via hepatocyte growth factor (HGF) mediated crosstalk between tumor cells and stromal cells in lung cancer." (PMID 30680600, 2019). "This study was performed to investigate whether miR‐1‐3p and miR‐206 increased the sensitivity of HGF‐induced gefitinib resistance in EGFR mutant lung cancer cells." (PMID 29664235, 2018). "To determine whether PDBu or HGF could affect the cortactin expression, we tested cortactin expression and the cell migration and invasion ability in PDBu- or HGF-induced lung cancer cells." (PMID 29986736, 2018). "To test the relevance of HGF production by fibroblasts in modulating cancer cell phenotype, we performed migration assays with different lung cancer cells testing the stimulatory potential of medium collected from several primary cell lines of lung fibroblasts isolated from lung cancer patients." (PMID 29558956, 2018). "(2006) suggested that cigarette smoke could overexpress HGF in type II pneumocytes and lung cancer cells." (PMID 29570930, 2018). "Besides, in lung cancer models, CAFs obtained from lung cancer tissue produce hepatocyte growth factor (HGF), thereby activating the EMT-related c-Met pathway." (PMID 30405720, 2018). "Moreover, the levels of HGF are increased in lung cancer tissue compared to normal lung mucosa, suggesting that inhibition of pro-HGF activation is a valid approach to inhibit HGF/MET signaling." (PMID 28968967, 2017). "The receptor tyrosine kinase MET and its ligand, the hepatocyte growth factor, are essential to embryonic development, whereas deregulation of MET signaling is associated with tumorigenesis leading to various cancers, including lung carcinoma." (PMID 28061464, 2017). "Moreover, the usefulness of the inhibition of the HGF/Met pathway for the treatment of EGFR-TKI-resistant lung cancer cells has been reported." (PMID 28619066, 2017). "Moreover, the significance of the HGF/Met pathway on lung cancer progression has increasingly been reported." (PMID 28619066, 2017). "Interestingly, when cultured in lung cancer cell-conditioned media, lung fibroblasts produced HGF to a greater extent than when they were cultured in control conditions (i.e., regular fibroblast-conditioned media)." (PMID 28619066, 2017).
lung carcinoma (continued). "Indeed, in one study, exogenous HGF induced resistance to an anti-EGFR antibody in lung cancer cells (via the Met/Gab1/Akt signaling pathway)." (PMID 28619066, 2017). "The identification of the specific factor that is released from lung cancer cells that stimulates HGF production by fibroblasts might also be useful for the development of a novel strategy for lung cancer treatment." (PMID 28619066, 2017). "In addition, we further confirmed the inhibition of the c-Met pathway by IRCR201 under the presence of HGF in A549, an HGF-dependent lung cancer cell line." (PMID 28902178, 2017). "Therefore, to explore the molecular mechanism by which HGF reduces sensitivity to gefitinib in lung cancer harboring wild-type EGFR, we examined the phosphorylation status of MET, EGFR, ErbB3, and the downstream signaling pathways by western blotting." (PMID 26919104, 2016). "Next, we explored whether inhibition of MET, the receptor of HGF, could restore the sensitivity to gefitinib in lung cancer cells with wild-type EGFR that were pretreated with HGF." (PMID 26919104, 2016). "We found that migration of HTB177 to HGF was inhibited when apyrase was added to the lower chamber, which confirms potential role of ATP in HGF induced migration of lung cancer cells." (PMID 26597723, 2015). "In particular, HGF is known to work in combination with EGF on lung cancer cells." (PMID 26310485, 2015). "Lung cancer may attract neutrophils to release their HGF storage and contribute to the local microenvironment for lung cancer progression." (PMID 26310485, 2015). "HGF receptor inhibitors have been shown to reverse HGF induced EMT in lung cancer cells." (PMID 26310485, 2015). "HGF has some well established effects on cancer cells, including lung cancer cells." (PMID 26310485, 2015). "It is concluded that YangZheng XiaoJi has a strong effect on HGF-induced cell adhesion and migration, which may be important when considering devising therapies in lung cancer and in the context of using the HGF/EGF receptor inhibitors in lung cancer." (PMID 26310485, 2015). "HGF can be produced by stromal fibroblasts in a tumor microenvironment and is responsible for activation of the HGF/c-Met signaling during the advancement of lung cancer." (PMID 26115510, 2015). "Finally, significant correlations between tumor Met content and treatment response have been reported for HGF/Met pathway inhibitors in advanced gastric and lung cancers." (PMID 25335552, 2014). "For example, EGFR-TKI resistance could be caused by MET amplification, HGF-triggered MET activation, Gas6-triggered AXL activation, and HER2 amplification in EGFR mutant lung cancer." (PMID 24952482, 2014). "A similar study demonstrated that c-Met may be activated via an HGF-independent signaling pathway, following transfection, in lung cancer." (PMID 25202379, 2014). "The purpose of this study was to examine whether 2 clinically approved mTOR inhibitors, temsirolimus and everolimus, overcome HGF-dependent resistance to EGFR-TKIs in EGFR mutant lung cancer cells." (PMID 23690929, 2013). "Taken together, these results suggest that crizotinib plus either afatinib or WZ4002 may overcome the resistance to reversible EGFR-TKIs of EGFR mutant lung cancer cells containing an EGFR gatekeeper mutation, Met gene amplification, and/or HGF overexpression." (PMID 24386407, 2013). "Based on the concept that inhibition of PI3K/AKT pathway may effectively overcome HGF-induced resistance to gefitinib, we hypothesized that bufalin could reverse EGFR-TKIs resistance induced by HGF in EGFR mutant lung cancer." (PMID 23533466, 2013). "HGF-induced c-Met-ERK-COX2 signaling is known to be involved in lung cancer invasion." (PMID 23878598, 2013). "Cigarette nicotine is also responsible for HGF production in lung cancer." (PMID 23296269, 2013). "We next evaluated whether mTOR inhibitors would control the growth of EGFR mutant lung cancer cells with HGF-triggered EGFR-TKI-resistance in vivo." (PMID 23690929, 2013).